Y_RNA (Y RNA )
Gene: Miscellaneous RNA gene on chromosome 14 (102,695,388 to 102,695,495, forward strand). Ensembl gene ENSG00000202459.
Homologues: Orthologues: chimpanzee Y_RNA (97% identical), macaque Y_RNA (94% identical). Paralogues in human: RNY1 (85% identical), Y_RNA (82% identical), Y_RNA (81% identical), Y_RNA (80% identical), Y_RNA (79% identical), Y_RNA (78% identical), RNY1P8 (77% identical), Y_RNA (77% identical), RNY1P11 (76% identical), RNY1P12 (76% identical), RNY1P5 (76% identical), Y_RNA (76% identical), and 93 more.